CAPG (capping actin protein, gelsolin like)
Diseases named in the same sentence as CAPG in open-access papers (continued):
Sharing a sentence is not in itself a finding about the gene and the disease.
gastric cancer (4 papers, 2018 to 2025). A primary or metastatic malignant neoplasm involving the stomach. "It has been reported that CAPG is identified as a novel biomarker for early gastric cancer, contributing to tumour development through the Wnt/beta‐catenin signalling pathway." (PMID 40982354, 2025). "CAPG has been shown to facilitate gastric cancer proliferation, migration, invasion, and metastasis in both in vivo and in vitro models." (PMID 41050938, 2025). "We demonstrate that CAPG expression is upregulated in gastric cancer (GC) especially EGC." (PMID 38191512, 2024). "We present the first study of the mechanism of action of CAPG in early gastric cancer (EGC)." (PMID 38191512, 2024). "The previous study demonstrated CapG lost exhibiting in the small-cell lung cancer (H69, Lu22, Lu139, Lu134, and H209), lung adenocarcinoma (PC7, RERF-LCMS), gastric cancer (AZ521), and melanoma (A2058)." (PMID 30155403, 2018).
glioblastoma (4 papers, 2008 to 2023). The most malignant astrocytic tumor (WHO grade IV). "Increased CAPG expression has been correlated with elevated invasiveness and migration in several human tumor entities like, e.g., glioblastoma." (PMID 36993823, 2023). "CAPG was identified to be up-regulated in glioblastoma cell lines in previous study and GLIS3 was found to be an overexpressed gene in GBM tissues." (PMID 36114444, 2022).
lymph node metastasis (4 papers, 2018 to 2024). "In addition, the previous report showed that patients with lymph node metastases were associated with overexpression of CapG in 75 pulmonary adenocarcinomas." (PMID 30155403, 2018). "Overexpression of CAPG was statistically correlated with poor survival, lymph node metastasis and advanced tumor stage." (PMID 37354358, 2023). "Proteomic analysis has revealed CAPG overexpression in GC cells with lymph node metastasis." (PMID 32099594, 2019). "However, our findings showed that CAPG was negatively correlated with lymph node metastasis." (PMID 38191512, 2024). "In addition, CAPG was strongly correlated with lymph node metastasis, and CAPG expression was higher in tissues without lymph node metastasis (p = 0.00002)." (PMID 38191512, 2024). "We demonstrated that CAPG is upregulated in EGC, especially in samples without lymph node metastasis, and that CAPG promotes GC proliferation, migration, invasion, and metastasis in vivo and in vitro." (PMID 38191512, 2024).
melanoma (4 papers, 2011 to 2024). A malignant, usually aggressive tumor composed of atypical, neoplastic melanocytes. "Interestingly, Enolase 2 and CapG are used as tumour markers in the diagnosis and prognosis of several cancer types, and both proteins have been associated with cell proliferation, invasion, migration, and metastatic capacity in several types of cancer, including melanoma." (PMID 34885166, 2021). "We then investigated the expression of TSPAN8 and CAPG protein on another seven melanoma cell lines/clones, in addition to the two clones, to find any correlation with the invasive potential of melanoma cells." (PMID 21081927, 2011). "Therefore, the cell surface expression of TSPAN8, but not that of CAPG, was associated with the invasive behaviour of a panel of melanoma cells in culture." (PMID 21081927, 2011). "Melanoma cells were surface stained for TSPAN8, RELN and FXYD5 or intracellularly stained for renalase, CAPG, BCL11A and ID3." (PMID 21081927, 2011).
bone metastasis (3 papers, 2018 to 2023). Transfer of a neoplasm from its primary site to bones. "Patients with high expression of CAPG and GIPC1 treated with zoledronic acid showed a tenfold reduction in the risk of bone metastasis compared to the control group (P = 0.008)." (PMID 38041134, 2023). "CAPG showed a weak association, and GIPC1 expressed a stronger relation with bone metastasis." (PMID 30155403, 2018). "Using primary tumor tissue from patients in the AZURE study, we showed that a novel composite biomarker comprising the proteins CAPG and GIPC1 was prognostic for developing bone metastasis (HR = 4.5, 95% CI = 2.1 to 9.8, P < .001) and predicted response to zoledronate (P = .008)." (PMID 29425304, 2018).
pancreatic ductal adenocarcinoma (3 papers, 2008 to 2026). An infiltrating adenocarcinoma that arises from the epithelial cells of the pancreas. "The actin-binding protein CAPG (Capping Actin Protein, Gelsolin Like) is implicated in oncogenesis, but its role in pancreatic ductal adenocarcinoma (PDAC) remains unclear." (PMID 41915646, 2026). "In pancreatic ductal adenocarcinomas, a clinical study also showed that high CapG expression was correlated with increased tumour size, which was consistent with results obtained in the current study." (PMID 18237446, 2008).
acute myeloid leukemia (2 papers, 2023 to 2025). Acute myeloid leukemia (AML) is a group of neoplasms arising from precursor cells committed to the myeloid cell-line differentiation. "Super-enhancers associated gene CAPG (Capping actin protein, gelsolin-like) regulates Nf-κB signaling in acute myeloid leukemia in a MLL-AF9 mouse model." (PMID 37296281, 2023). "In this study, we identified SE-associated genes by integrating cell-specific SEs with RNA-seq data and found six genes (CAPG, CD207, GPR132, SLC7A11, HIPK3 and FCER1G) that are correlated with poor prognosis in acute myeloid leukemia (AML) patients according to the TCGA-LAML database." (PMID 37296281, 2023).
gynecologic cancers (2 papers, 2014 to 2022). "This review highlights differential protein distribution of two exemplary proteins, beta-catenin and CapG, and their role in gynecologic cancers." (PMID 36230711, 2022).
metastatic cancers (2 papers, 2023). A carcinoma which has spread from the original site of growth to another anatomic site. "Increased CAPG expression has been found in several metastatic cancers, suggesting its role in cancer cell invasion and metastasis." (PMID 37296281, 2023). "One of the upregulated genes potentially driving the oncogenic role of INPP4B in RB is the macrophage-capping protein (CAPG) which raised the expression of CAPG was likewise shown in different metastatic cancers, supporting its involvement in tumor cell invasion and metastatic processes." (PMID 36993823, 2023).
pulmonary arterial hypertension (2 papers, 2022 to 2024). Pulmonary arterial hypertension (PAH) is a group of diseases characterized by mean pulmonary artery pressure >20 mmHg and elevated pulmonary arterial resistance leading to right heart failure. "Knockdown of the gelsolin-like protein CapG in pulmonary arterial smooth muscle cells (PASMCs) causes reduced proliferation, enhanced apoptosis and cell cycle arrest, while its downregulation attenuates pulmonary hypertension." (PMID 36098487, 2022). "In contrast, Yorkshire pigs, being an exotic species, exhibit increased expression of the CapG gene under hypoxic conditions, potentially to alleviate pulmonary arterial hypertension and adapt to the hypoxic environment." (PMID 38680426, 2024).
Rett syndrome (2 papers, 2019 to 2021). A severe neurodevelopmental disorder affecting the central nervous system.
Allergy (1 paper, 2022). An allergy is an immune response or reaction to substances that are usually not harmful. "This protein group includes proteins involved in cell stress response (HSPB1), mucosal protection and allergy (MUC1), complement activation (CD55) and actin polymerization (CAPG, APRT, TPPP3)." (PMID 35590254, 2022).
amyloid (1 paper, 2023). "Furthermore, according to previously published data, protein levels of FABP3 and CAPG may increase in an age-dependent manner in microglia of amyloid mouse models, while the protein levels of MDH1 appear to decrease in the very same mice." (PMID 37775827, 2023).
anaplastic large cell lymphoma (1 paper, 2022). Anaplastic large cell lymphoma (ALCL) is a rare and aggressive peripheral T-cell non-Hodgkin lymphoma, belonging to the group of CD30-positive lymphoproliferative disorders, which affects lymph nodes and extranodal sites. "Gene set enrichment analysis revealed that NK(EGR1) and NK(CAPG) were closely related to tumour metastasis, as shown by kidney cancer metastasis to Hodgkin lymphoma, T-cell leukaemia, and Ki-1+ anaplastic large cell lymphoma." (PMID 36046723, 2022). "Compared to that in the normal kidney cells, the NK(EGR1) and NK(CAPG) subpopulations were abnormally elevated in ccRCC and could mediate ccRCC metastasis, such as Hodgkin's lymphoma, T-cell leukaemia, and Ki-1+ anaplastic large cell lymphoma development in kidney cancer." (PMID 36046723, 2022).
atherosclerosis (1 paper, 2026). A disease characterized by the build-up of fatty material and calcium deposition in the arterial wall resulting in partial or complete occlusion of the arterial lumen. "Additionally, CAPG enhances the inflammatory response in adipocytes, potentially serving as a key molecule mediating obesity-related atherosclerosis." (PMID 41695716, 2026).
bladder transitional cell carcinoma (1 paper, 2023). The most common morphologic subtype of urinary bladder carcinoma (over 90% of cases). "Increasing cell motility by up-regulation of CAPG might also lead to tumorigenesis and enhanced metastasis in bladder transitional cell carcinoma." (PMID 37501157, 2023).
bone cancer (1 paper, 2023). A primary or metastatic malignant neoplasm affecting the bone or articular cartilage. "CAPG, a gelsolin protein family member which regulates actin filament remodeling, has been shown to be a prognostic marker in both breast and bone cancer." (PMID 38132437, 2023).
cervical cancer (1 paper, 2023). A primary or metastatic malignant neoplasm involving the cervix. "By contrast, NDC80 and CAPG are a novel targets in the survival of cervical cancer." (PMID 36723760, 2023).
diffuse large B-cell lymphoma (1 paper, 2023). "CAPG enhances the proliferation and invasion of diffuse large B-cell lymphoma cells, inhibits apoptosis, and activates the PI3K/AKT signaling pathway." (PMID 37434120, 2023). "Cells and tissues from diffuse large B-cell lymphoma expressed CAPG at high levels." (PMID 37434120, 2023).
emphysema (1 paper, 2023). "To address this, we analyzed the inflammatory status and the dynamic state of CapG in the lungs in the emphysema mouse model." (PMID 37454739, 2023).
fallopian tube carcinoma (1 paper, 2014). A carcinoma that arises from epithelial cells of the fallopian tube. "Although mechanisms are still to explore, the positive correlation of SNP rs6886 as a possible functional relevant CapG variant with FTC may introduce a novel interesting link between ovarian and fallopian tube carcinomas." (PMID 24804218, 2014).
glaucoma (1 paper, 2008). Increased pressure in the eyeball due to obstruction of the outflow of aqueous humor. "There is evidence that CAPG is regulated by elements of the AP-1 transcription factor complex, which was activated in the primate model of glaucoma." (PMID 18822132, 2008). "Differential expression of motility genes, including capping protein G (CAPG) and transforming growth factor beta-induced (TGFBI), was consistent with the reactive, migratory astrocyte phenotype characteristic of glaucoma, as were ECM remodeling genes, such as GPNMB and TIMP1." (PMID 18822132, 2008).
Hearing impairment (1 paper, 2019). A decreased magnitude of the sensory perception of sound. "Recently, a homozygous deletion affecting the last three exons of ELMOD3, the entire CAPG gene, and the first non-coding exon of SH2D6 has been identified in a Tunisian ASD proband with ID and hearing impairment." (PMID 30736458, 2019).
Insulin resistance (1 paper, 2025). Increased resistance towards insulin, that is, diminished effectiveness of insulin in reducing blood glucose levels. "In T2DM, M1 macrophage polarization exacerbates adipose tissue inflammation and insulin resistance, whereas high expression of CAPG may amplify this process by enhancing the migration of monocytes to inflammatory sites." (PMID 41050938, 2025).
lung carcinoma (1 paper, 2025). "Elevated CAPG expression has been demonstrated to accelerate the expansion and spread of lung cancer cells and has been linked with lung cancer malignancy and prognosis." (PMID 38700746, 2025).
monocytic leukemia (1 paper, 2023). "Moreover, we also found that langerin and CapG are endogenously expressed in a human monocytic leukemia cell line, THP-1 cells." (PMID 37454739, 2023). "To further examine the function of CapG, we analyzed the subcellular localization of CapG in murine BMDCs and in a human promyelocytic leukemia cell line: HL-60, a human monocytic leukemia cell line: THP-1, and in U937 cells: a human diffuse histiocytic lymphoma cell line." (PMID 37454739, 2023).
nasopharyngeal carcinoma (1 paper, 2022). A carcinoma arising from the nasopharyngeal epithelium. "The motility-associated functions and potential molecular mechanisms of CapG in nasopharyngeal carcinoma (NPC) remain unclear." (PMID 36258216, 2022).
oral cancer (1 paper, 2008). "Because OSCC is also a solid neoplasm exhibiting aggressive tumour phenotypes, we hypothesized that CapG is a potential emerging therapeutic target of interest for the treatment of oral cancer." (PMID 18237446, 2008). "Evidence indicates that CapG also possesses an oncogenic function involved in the control of cell migration or invasion, and we hypothesized that the protein has potential as an emerging therapeutic target of interest for the treatment of oral cancer." (PMID 18237446, 2008).
oral premalignant lesions (1 paper, 2008). "The purpose of the current study was to determine CapG protein/mRNA expression in a series of human primary OSCCs and human oral premalignant lesions(OPLs) and correlate the protein expression with the clinical relevance in patients with OSCC." (PMID 18237446, 2008). "In the current study, to further determine the potential involvement of CapG in OSCC, we evaluated the status of CapG protein and mRNA expression in human oral premalignant lesions (OPLs) and primary OSCCs and correlated the results with clinicopathologic variables." (PMID 18237446, 2008).
oral squamous-cell carcinoma (1 paper, 2008). "We previously applied proteomic methods to characterize differentially expressed proteins in oral squamous-cell carcinoma (OSCC) cells and detected significantly high expression levels of CapG in OSCC-derived cell lines compared to human normal oral keratinocytes." (PMID 18237446, 2008).
ovarian serous adenocarcinoma (1 paper, 2009). An adenocarcinoma that arises from the ovary and is characterized by the presence of malignant epithelial cells that, in well differentiated tumors, resemble the epithelium of the fallopian tube or, in poorly differentiated tumors, show anaplastic features and marked nuclear atypia. "Even though we did not detect any differences in relation to survival in our analysis, the expression of CLU, CAPG, and PRAME might still be associated with the development and progression of serous ovarian adenocarcinomas." (PMID 19775429, 2009). "In this study, we performed an external validation of four potential prognostic biomarkers, ITGB3, CLU, CAPG, and PRAME, in advanced ovarian serous adenocarcinomas." (PMID 19775429, 2009).
rheumatoid arthritis (1 paper, 2014). A chronic, systemic autoimmune disorder characterized by inflammation in the synovial membranes and articular surfaces. "We confirmed the upregulation of CAPG in rheumatoid arthritis synovial fluid by multiple reaction monitoring assay as well as by Western blot." (PMID 24393543, 2014). "Proteins not previously reported to be associated with rheumatoid arthritis including, coronin-1A (CORO1A), fibrinogen like-2 (FGL2), and macrophage capping protein (CAPG) were found to be upregulated in rheumatoid arthritis." (PMID 24393543, 2014).
Sepsis (1 paper, 2025). Sepsis is defined as life-threatening organ dysfunction caused by a dysregulated host response to infection. "The GSEA findings indicated that CAPG and DDAH2 were strongly implicated in “FC gamma R-mediated phagocytosis” and “Ribosome” in both T2DM and sepsis, further indicating they share the same mechanism of immunometabolic reprogramming." (PMID 41050938, 2025). "In sepsis, the overactivation of M1 macrophages is an important driver of the “cytokine storm” with CAPG potentially contributing to the immune imbalance by regulating macrophage phagocytosis." (PMID 41050938, 2025). "In sepsis, CAPG and DDAH2 these genes showed broader functional repertoires, including Antigen processing and presentation, complement activation, and T cell receptor signalings." (PMID 41050938, 2025). "Subsequently, expression analysis revealed that in both training and validation sets for T2DM and sepsis, CAPG and DDAH2 were significantly highly expressed in the disease group." (PMID 41050938, 2025). "CAPG and DDAH2, as key node genes, not only serve as early diagnostic biomarkers but also possibly influence diseases by the immune-metabolism pathway, proving a theoretical foundation for the development of stem cell-based combination therapies in T2DM and sepsis." (PMID 41050938, 2025). "In this study, we identified two shared stem cell-related biomarkers (CAPG and DDAH2) for T2DM and sepsis and further validated the expression of biomarkers through in vitro cell experiments." (PMID 41050938, 2025). "Two common stem cell-related biomarkers (CAPG and DDAH2) and their common pathways between T2DM and sepsis were discovered, providing new insights for further molecular mechanism studies." (PMID 41050938, 2025). "At transcription and protein levels, CAPG and DDAH2 were significantly more highly expressed in the T2DM-sepsis model than in the controls." (PMID 41050938, 2025). "Functional enrichment analysis using GO and KEGG databases revealed that CAPG and DDAH2 exhibit convergent roles in T2DM and sepsis." (PMID 41050938, 2025). "Through a comprehensive analysis, CAPG and DDAH2 were found and those were significantly highly expressed in both T2DM and sepsis." (PMID 41050938, 2025). "In our study, CAPG showed significant correlations with monocytes and macrophages in both T2DM and sepsis, revealing that it may be involved in T2DM and sepsis by affecting monocyte/macrophage functions, such as phagocytosis and chemotaxis, thereby broadening its pathophysiological role." (PMID 41050938, 2025). "In summary, these findings highlight the complex roles of CAPG and DDAH2 in modulating immune cell functions in both T2DM and sepsis, suggesting that targeting these proteins may offer potential therapeutic strategies for managing inflammation and immune dysregulation in these diseases." (PMID 41050938, 2025). "Therefore, CAPG and DDAH2 were shared stem cell-related biomarkers for T2DM and sepsis." (PMID 41050938, 2025).
serous adenocarcinoma (1 paper, 2009). An adenocarcinoma that is characterized by the presence of papillary patterns and cellular budding. "We analysed the gene expression of CLU, ITGB3, CAPG, and PRAME in 30 advanced staged serous adenocarcinomas with quantitative real-time polymerase chain reaction (QPCR) and the protein levels were analysed in 98 serous adenocarcinomas with western blot for semiquantitative analysis." (PMID 19775429, 2009).
virus infection (1 paper, 2022). "The two clonal cell lines with low but detectable expression of CAPG showed a 4-fold block in virus infection, with replication remaining low at all time points." (PMID 36146710, 2022).